ASH1L-AS1 (ASH1L antisense RNA 1)
Synonyms: APPLE
Gene: Long non-coding RNA gene on chromosome 1 (155,562,026 to 155,570,755, forward strand). Ensembl gene ENSG00000235919.
Diseases named in the same sentence as ASH1L-AS1 in open-access papers:
ASH1L-AS1 is named in the same sentence as 5 diseases in open-access papers, as found by Europe PMC text mining. Sharing a sentence is not in itself a finding about the gene and the disease. The quoted sentences say what the papers report.
tumor (2 papers, 2025). "These insights underscore the multifaceted role of ASH1L-AS1/APPLE in tumor biology, spanning proliferation, immune modulation, sex-specific regulation, and MAPK pathway reprogramming." (PMID 40646641, 2025). "LncRNA ASH1L-AS1 has the potential to encode a microprotein, APPLE, which is stably expressed in HCC cells and continuously upregulated in tumor tissues." (PMID 41186893, 2025). "Beyond its role in MAPK activation, our additional analyses suggest that ASH1L-AS1/APPLE may also contribute to shaping the tumor immune microenvironment." (PMID 40646641, 2025). "We confirmed that ASH1L-AS1 encodes a microprotein, APPLE, which is stably expressed in HCC cells and consistently upregulated in tumor tissues regardless of RAS mutation status." (PMID 40646641, 2025).
ASH1L-AS1 also shares sentences with these, for which no sentence is quoted: acute myeloid leukemia (2 papers); cancer (2); Arrhythmia (1); hepatocellular carcinoma (1).